FGF2 (fibroblast growth factor 2)
Diseases named in the same sentence as FGF2 in open-access papers (continued):
Sharing a sentence is not in itself a finding about the gene and the disease.
viral infection (13 papers, 2012 to 2026). "Transforming growth factor-beta 1 (TGF-β1) secreted by tumor cells promotes OV infection in CAFs, while high levels of fibroblast growth factor 2 (FGF2) make tumor cells more susceptible to viral infection." (PMID 39337402, 2024). "At the same time, tumor cells can produce high levels of fibroblast growth factor 2 (FGF2) to render them sensitive to viral infection." (PMID 38169820, 2023). "Increased progenitor cell marker expression (alongside decreased β-cell markers) was previously shown in FGF2- and viral infection-induced dedifferentiation models in EndoC-βH1 cells." (PMID 34804002, 2021). "Whereas upon viral infection, FGF2 suppresses antiviral signaling by inhibiting the interaction of activated RIG-1 with downstream mitochondrial antiviral-signaling protein (MAVS) and type I interferon production." (PMID 32300593, 2020). "For example, an anti-inflammatory crosstalk between tumor cells and tumor-associated fibroblasts mediated by transforming growth factor-β (TGF-β) and fibroblast growth factor 2 (FGF2), respectively, has been found to sensitize both tumor cells and fibroblasts for viral infection." (PMID 34696274, 2021). "This inconsistency might be due to the difference between cytosolic and secreted FGF2 protein in AECs upon viral infection." (PMID 32300593, 2020). "In addition, unlike in the absence of these growth factors, we found that even a single NeuroD1-virus infection together with FGF2 and EGF could effectively induce AtN conversion by 7 dpt." (PMID 36289433, 2022). "We found that FGF2 and EGF stimulation allowed NR-astrocytes exposed to a single NeuroD1 virus infection to be converted into neurons." (PMID 36289433, 2022). "For example, in Liu’s study, cytosolic FGF2 stabilizes inactivated retinoic-acid inducible gene-1 (RIG-1), the primary pathogen recognition receptor (PRR) against virus infection, via preventing proteasome-mediated RIG-1 degradation in physiological conditions." (PMID 32300593, 2020). "The aberrant activation of the fibroblast growth factor 2 (FGF2)/fibroblast growth factor receptor (FGFR) signaling pathway drives several pathologies, including cancer development, metastasis formation, resistance to therapy, angiogenesis-driven pathologies, vascular diseases, and viral infections." (PMID 36142770, 2022).
colitis (12 papers, 2017 to 2025). Inflammation of the colon. "FGF2 cooperates with IL-17 to repair damaged epithelium and control microbes outgrowth, to suppress colitis and colon carcinoma associated with colitis." (PMID 29997586, 2018). "For example, Tregs release keratinocyte growth factor (KGF) to support alveolar regeneration after lung damage and fibroblast growth factor 2 (FGF2) to enhance intestinal epithelial growth during colitis." (PMID 40948794, 2025). "We have recently reported that FGF2 cooperates with IL-17 to protect intestinal epithelium during dextran sodium sulfate (DSS)-induced colitis." (PMID 28765647, 2017). "During colitis, FGF-2 signaling is essential for maintaining gut homeostasis." (PMID 36836678, 2023). "Moreover, dysregulated microbiota-triggered TGF-β1 influenced FGF-2 production in Treg cells during colitis, and cooperative effects between FGF-2 and IL-17A contributed to the regeneration of damaged intestinal epithelium." (PMID 36064450, 2022). "Specifically, FGF2 has been shown to cooperate with IL‐17 to accelerate proliferation and repair the damaged intestinal epithelium in a dextran sulfate sodium salt‐induced mouse colitis model." (PMID 36051984, 2022). "Administration of exogenous recombinant FGF2 alleviates DSS-induced colitis." (PMID 34136479, 2021). "Recombinant FGF10 may recruit T-regulatory cells at the site of inflammation, similarly to Fgf2 in the DSS-colitis model, and thereby stimulate the release of IL17, to drive repair and homeostasis." (PMID 34136479, 2021). "The fibroblast growth factor 2 (FGF2) gene seems to coordinate with IL-17 to stimulate the genes to work to repair the damaged epithelium in colitis diseases, which could indicate the importance of FGF2 in repairing the intestinal epithelium after parasite damage." (PMID 38397178, 2024). "In dextran sodium sulfate (DSS)-induced colitis, TGF-β from damaged epithelium triggered fibroblast growth factor 2 (FGF2) production in Tregs." (PMID 36696569, 2023).
heart failure (12 papers, 2015 to 2025). Inability of the heart to pump blood at an adequate rate to meet tissue metabolic requirements. "Elevated serum FGF2 level is strongly associated with an increased risk of heart failure and could serve as a useful biomarker to complement vital diagnostic parameters for heart failure." (PMID 38355415, 2024). "Additionally, to evaluate the possible correlation between serum FGF2 levels and its diagnostic parameters in patients with heart failure." (PMID 38355415, 2024). "Possible correlations between serum FGF2 levels and other prognostic parameters in patients with heart failure were analyzed." (PMID 38355415, 2024). "Receiver operating characteristic curve analysis identified FGF2 concentration as a significant predictor in heart failure diagnosis, with an area under the curve of 0.8693 (p < 0.0001)." (PMID 38355415, 2024). "ESCs-derived exosomes evidently attenuated TAC-induced heart failure, improving cardiac function and promoting myocardial angiogenesis which can be attenuated by selective FGF2 inhibitor AZD4547." (PMID 34262947, 2021). "Fibroblast growth factor-2 (FGF2) may serve as a diagnostic biomarker for heart failure due to its ability to promote cardiac fibrosis and hypertrophy; however, the relationship between FGF2 concentration and heart failure is unclear." (PMID 38355415, 2024). "Importantly, in the heart failure group, serum FGF2 concentrations correlated with key prognostic parameters for heart failure, such as reduced left ventricular ejection fraction and elevated serum levels of N-terminal pro-B-type natriuretic peptide." (PMID 38355415, 2024). "Indeed, combined gene therapy has recently shown significant promise in the treatment of animal models of heart failure, with combined transfer of apelin, fibroblast growth factor-2, and SERCA2a demonstrating increased gene expression in ischemic heart failure model." (PMID 29621141, 2018). "Serum FGF2 levels were higher in patients with heart failure (125.60 [88.95, 183.40] pg/mL) than in those with non-heart-failure dyspnea (65.30 [28.85, 78.95] pg/mL) and healthy controls (78.90 [60.80, 87.20] pg/mL) (p < 0.001)." (PMID 38355415, 2024). "A similar interaction between FGF2 and ERK1/2 in cardiac fibroblasts plays a role in the development of lipopolysaccharide (LPS)-triggered cardiac adverse events, leading to fibrosis and heart failure." (PMID 34095143, 2021). "Therefore, this study aimed to explore whether FGF2 could aid in distinguishing patients with heart failure from healthy controls and those with dyspnea without heart failure." (PMID 38355415, 2024).
myocardial ischemia (12 papers, 2015 to 2023). A disorder of cardiac function caused by insufficient blood flow to the muscle tissue of the heart. "Our results suggest that human growth factor/IgG and FGF2/Fc- fusion complexes have potential to provide a biologics platform to treat myocardial ischemia-reperfusion and other forms of tissue injury." (PMID 35295649, 2022). "We find that endogenous FGF2 mediates cell survival, postischemic functional recovery, vascular remodeling, and the cardiac hypertrophic response in a closed‐chest model of cardiac ischemia‐reperfusion injury." (PMID 25626875, 2015). "Our transcriptional data provide evidence that significantly higher levels of hypoxia-related and proangiogenic genes (HIF1a, VEGFA, FGF2, eNOS, SOX17, and LRG1) promote neovascularization at the site of increased cardiac ischemia." (PMID 36371548, 2023).
renal carcinoma (12 papers, 1997 to 2024). A carcinoma arising from the epithelium of the renal parenchyma or the renal pelvis. "It has been shown that miR 203 inhibits renal cancer cell proliferation, migration and invasion by targeting of FGF2." (PMID 34316330, 2021). "For example, PCGEM1/miR-433-3p/FGF2 signaling pathway contributes to malignant phenotypes of renal carcinoma cells." (PMID 33088221, 2020). "The restoration of FGF2 markedly attenuated tumor suppressive effects of miR-203 on renal cancer cells." (PMID 25890121, 2015). "Further investigation showed that ectopic expression of FGF2 partially reversed the inhibition effect of enforced miR-203 expression on the malignant phenotypes of renal cancer cells." (PMID 25890121, 2015). "Taken together, these data suggested that miR-203 impacted on renal cancer cells partially by inactivation of FGF2." (PMID 25890121, 2015). "In renal cancer, FGF2 enhances cell proliferation by triggering the FGFR2 signalling pathway." (PMID 39091947, 2024). "Ectopic expression of miR-203 could inhibit cell proliferation, migration and invasion capacity of renal cancer cells by targeting FGF2." (PMID 25890121, 2015). "Our study suggested that miR-203 could be a potential prognostic marker and functions as a tumor suppressor in human renal cancer by post-transcriptionally targeting FGF2." (PMID 25890121, 2015). "Moreover, rCSC-EVs, but not those derived from non-stem renal cancer cells, were shown to carry several mRNAs of proangiogenic genes, such as VEGF, fibroblast growth factor 2 (FGF2), angiopoietin 1, ephrin A3, MMP2, and MMP911." (PMID 30872568, 2019).
chronic obstructive pulmonary disease (11 papers, 2015 to 2024). A chronic and progressive lung disorder characterized by the loss of elasticity of the bronchial tree and the air sacs, destruction of the air sacs wall, thickening of the bronchial wall, and mucous accumulation in the bronchial tree. "Although the positive effects of recombinant fibroblast growth factor-2 (rFGF-2) in chronic obstructive pulmonary disease (COPD) have been implicated in previous studies, knowledge of its role in COPD remains limited." (PMID 30429461, 2018). "Studies have shown that serum samples from patients with chronic obstructive pulmonary disease have significantly lower levels of FGF2 compared to those from normal subjects." (PMID 38962005, 2024). "Studies on the role of the protein ‘fibroblast growth factor-2’ (FGF-2) in chronic obstructive pulmonary disease (COPD) suggest that inhaled FGF-2 could help treat the emphysema linked to smoking." (PMID 30429461, 2018). "According to literature reports, related studies on mast-cell-derived FGF2 mainly focus on angiogenesis, fibrosis, wound healing, and diseases involving hypertensive renal damage, airway hyperresponsiveness, chronic obstructive pulmonary disease and other diseases." (PMID 36845134, 2023). "According to literature, the research on mast cell-derived fibroblast growth factor (FGF2) mainly focuses on angiogenesis, fibrosis, wound healing, hypertension, kidney damage, airway hyperresponsiveness, chronic obstructive pulmonary disease, and other diseases." (PMID 36845134, 2023). "Furthermore, chronic obstructive pulmonary disease (COPD) is associated with enhanced bronchial expression of FGF1 and FGFR1 as well as FGF2." (PMID 26138239, 2015).
leiomyoma (11 papers, 2007 to 2026). A well-circumscribed benign smooth muscle neoplasm characterized by the presence of spindle cells with cigar-shaped nuclei, interlacing fascicles, and a whorled pattern. "Acidic FGF (aFGF or FGF-1) shows higher expression in leiomyomas compared with the surrounding myometrium, while basic FGF (bFGF or FGF-2) is excreted mainly by smooth muscle cells (SMCs) and macrophages." (PMID 41514933, 2026). "Because SPARC regulates cell–matrix interactions and also regulates the activity of many growth factors, such as fibroblast growth factor (FGF)-2, vascular endothelial growth factor (VEGF), and platelet-derived growth factor (PDGF), it could play a significant role in leiomyoma pathogenesis." (PMID 35641855, 2022).
diabetic foot ulcers (10 papers, 2016 to 2025). "The effect of rh-FGF2 on diabetic foot ulcers management showed a variable effect." (PMID 29949887, 2018). "FGF1, FGF2, FGF4, FGF7, FGF16, FGF21, and FGF23 have been found to have good therapeutic outcomes for diabetic foot ulcers." (PMID 34831463, 2021).
diabetic retinopathy (10 papers, 2012 to 2026). "Three secreted angiogenic factors-Fgf2, Pgf, and Lcn2-known to contribute to diabetic retinopathy, were induced." (PMID 42103933, 2026).
injury (10 papers, 2013 to 2024). Damage inflicted on the body as the direct or indirect result of an external force, with or without disruption of structural continuity. "Housing animals in an EE several weeks before brain injury results in a 50% increase in the expression of FGF-2 and attenuates functional deficits." (PMID 24098645, 2013).
lymphoma (10 papers, 2002 to 2024). A malignant (clonal) proliferation of B- lymphocytes or T- lymphocytes which involves the lymph nodes, bone marrow and/or extranodal sites. "GNG7, AXIN2, HIF1A, FGF2 and PPAP2B are found upregulated in our study in the same way as it is found in association with lymphoma disease according to literature." (PMID 30679748, 2019). "It has been reported that lymphoma cell lines express FGF2 and FGFRs and release FGF2 into culture media." (PMID 27007053, 2016). "Qualitative scoring by IHC on lymphoma tissue arrays showed that FGF2 and SDC1 expression were indeed specific to the HL tumor microenvironment." (PMID 23988031, 2013). "Also in lymphoma, FGF2 overexpression in diseased tissue biopsy samples is associated with chemoresistance and inferior progression free and overall survival." (PMID 23988031, 2013). "In lymphoma cells, syndecan-1 can regulate binding of FGF1 and FGF2, but only increases FGF2-dependent signaling." (PMID 34068954, 2021). "Although FGF2 may not always mediate SDC1 expression in cancers, SDC1 overexpression, at either a tissue or serum level, has been reported for multiple tumor types including solid tumors, lymphomas, and in a number of lymphoproliferative disorders." (PMID 23988031, 2013).
malignant glioma (10 papers, 2005 to 2024). A grade III or grade IV glioma arising from the central nervous system. "Studies have shown the FGF2 role in brain tumors, specifically malignant gliomas." (PMID 36505741, 2022). "FGF-2 is upregulated during reactive gliosis and overexpressed in malignant gliomas." (PMID 19018263, 2008).
multiple sclerosis (10 papers, 2013 to 2024). A progressive autoimmune disorder affecting the central nervous system resulting in demyelination. "Conversely, skewing signaling to favor FGFR1 also prevents the ability of FGF2 to induce MMPs implicated in blood-brain barrier damage and leucocyte recruitment in multiple sclerosis and other neurological diseases." (PMID 31856924, 2019). "Anosmin-1 and FGF-2 could possibly be diagnostic markers in multiple sclerosis (MS), because their expression level varies between different types of MS." (PMID 24735639, 2014). "FGF-2 and Anosmin-1, which are markers for the level of inflammation of multiple sclerosis lesions, participate in oligodendrocyte precursor cell migration via FGF receptor 1 (FGFR1)." (PMID 27642302, 2016). "Hippocampal insults have been observed in multiple sclerosis (MS) patients.Fibroblast growth factor-2 (FGF2) induces neurogenesis in the hippocampus and en-hances the proliferation, migration and differentiation of oligodendrocyte progenitor cells(OPCs)." (PMID 26464826, 2015). "Consistent with this notion, FGF2 expression is increased in demyelinated multiple sclerosis lesions and FGF2 null mice treated with cuprizone to induce demyelination showed enhanced remyelination relative to control mice suggesting that upregulated FGF2 expression was detrimental for OL/myelin." (PMID 39024549, 2024). "In accordance with the prominent role of FGF-2 in vivo is the finding of enhanced FGF-2 levels in multiple sclerosis lesions, which could originate from activated astrocytes and microglia and help to repopulate the tissue with OPCs." (PMID 24421756, 2013). "Expression of FGF2 was investigated in lesions and normal appearing white matter (NAWM) from seven cases of multiple sclerosis by immunohistochemistry and in situ hybridization." (PMID 31856924, 2019).
retinal degeneration (10 papers, 2012 to 2026). Degeneration of the retina. "Several studies of retinal degeneration report an increase in expression of neuroprotective factors such as Fgf-2 over time, which protects the retina by delaying, or in some cases, reducing photoreceptor cell death." (PMID 24134095, 2013). "Intravitreal delivery of LIF, CNTF, brain-derived neurotrophic factor (BDNF), or FGF2 promotes survival of photoreceptors after light damage or inherited retinal degeneration, and protects retinal ganglion cells after ischemic injury." (PMID 22701694, 2012). "Genetic models of retinal degeneration show increased FGF2 and leukemia inhibitory factor (LIF) expression." (PMID 22701694, 2012). "It is known that limited light stress activates the FGF2/gp130 signaling pathway and that prolonged exposure to light upregulates CNTF and FGF2, although usually at levels too low to protect against retinal degeneration." (PMID 32242818, 2020). "FGF2 and FGFR1 mRNA levels are greatly increased in light-induced retinal degeneration." (PMID 29312335, 2017).
chronic kidney disease (9 papers, 2013 to 2024). Impairment of the renal function secondary to chronic kidney damage persisting for three or more months. "FGF2 is highly associated with several kidney pathologies in both animal models and patients with chronic kidney disease." (PMID 32410988, 2020). "FGF2 treatment ameliorated renal functional and structural damage in experimental chronic kidney disease." (PMID 25811887, 2015). "Previous studies identified high levels of fibroblast growth factor-2 (FGF-2) in the plasma and urine of children with HIVAN and other HIV chronic kidney diseases (HIV-CKDs)." (PMID 34308967, 2021).
esophageal cancer (9 papers, 2015 to 2022). A primary or metastatic malignant neoplasm involving the esophagus. "Esophageal cancer studies have demonstrated that FGF2 overexpression is associated with a risk of recurrence of disease as well as reduced OS post-surgical resection." (PMID 33202734, 2020). "FGF2 as an important regulator of SPRY1 expression was involved in establishing the dysfunctional state of CD8+ T cells in esophageal cancer." (PMID 35785171, 2022). "Furthermore, FGF2 secreted from esophageal cancer cells promotes macrophage migration and survival through FGFR1 signaling." (PMID 31681612, 2019). "For example, in the tumor microenvironment of esophageal cancer, NCAM- and FGF-2-mediated FGFR1 signaling modulates the survival and migration of tumor-associated macrophages and cancer cells." (PMID 36303551, 2022). "In addition, the FGF2-mediated FGFR1 signaling pathway regulates the survival and migration of TAMs in the tumor microenvironment in esophageal cancer." (PMID 30811474, 2019).